PSMG1 (proteasome assembly chaperone 1)
Description:
Chaperone protein which promotes assembly of the 20S proteasome as part of a heterodimer with PSMG2. The PSMG1-PSMG2 heterodimer binds to the PSMA5 and PSMA7 proteasome subunits, promotes assembly of the proteasome alpha subunits into the heteroheptameric alpha ring and prevents alpha ring dimerization.
Synonyms: PAC-1; C21-LRP; Pba1; C21LRP; DSCR2; PAC1; LRPC21
Tractability: PROTAC: ubiquitination databases record sites on it; its protein half-life has been measured; a small molecule that binds it is known.
Gene: Protein-coding gene on chromosome 21 (39,174,769 to 39,183,503, reverse strand). Ensembl gene ENSG00000183527.
Subcellular location: Cytoplasm; Endoplasmic reticulum
Subcellular location (Human Protein Atlas): Cytosol; Golgi apparatus; Nucleoplasm
Pathways (Reactome):
Metabolism of proteins: Proteasome assembly
Gene Ontology:
Molecular function: molecular adaptor activity; protein binding; proteasome binding
Biological process: chaperone-mediated protein complex assembly; proteasome core complex assembly; proteasome assembly
Cellular component: cytoplasm; cytosol; endoplasmic reticulum; Golgi apparatus; nucleoplasm; nucleus; protein folding chaperone complex
Genetic constraint (gnomAD): Loss-of-function variants: 19 observed, 30.11 expected, observed/expected ratio (o/e) 0.63, 90% interval 0.44 to 0.93. The upper end of that interval is the gene's LOEUF score, 0.93, which puts it in group 3 of 6, group 1 being the genes least tolerant of losing a copy. Missense variants: 301 observed, 288.67 expected, observed/expected ratio (o/e) 1.04, 90% interval 0.95 to 1.15. Synonymous variants: 118 observed, 108.1 expected, observed/expected ratio (o/e) 1.09, 90% interval 0.94 to 1.27.
Homologues: Orthologues: chimpanzee PSMG1 (99% identical), macaque PSMG1 (98% identical), pig PSMG1 (93% identical), guinea pig PSMG1 (86% identical), mouse Psmg1 (85% identical), rat Psmg1 (73% identical), rabbit PSMG1 (73% identical), tropical clawed frog psmg1 (45% identical), zebrafish psmg1 (38% identical).
Diseases named in the same sentence as PSMG1 in open-access papers:
PSMG1 is named in the same sentence as 32 diseases in open-access papers, as found by Europe PMC text mining. Sharing a sentence is not in itself a finding about the gene and the disease. The quoted sentences say what the papers report.
breast carcinoma (5 papers, 2020 to 2026). "Basing on the database, we found that PSMG1 is highly co-expressed with NUP37 in breast cancer and also associated with poor prognosis in ER-positive patients." (PMID 34386417, 2021). "The PHF1 protein was shown to be overexpressed, while the SMCO4 and PSMG1 proteins had medium expression levels in breast carcinoma cells, all with low tissue specificity." (PMID 38138918, 2023). "Earlier studies have shown that PSMG1 is associated with increased susceptibility to inflammatory bowel disease, which can lead to diseases associated with colon cancer, whereas the co-expression relationship of NUP37 with PSMG1 was proposed to play a specific role in breast cancer." (PMID 38138918, 2023). "Therefore, to make a stronger elucidation of the connected function of NUP37 and PSMG1 in breast cancer, future exploration would be needed." (PMID 34386417, 2021). "The proteasome assembly chaperone (PSMG) gene family (comprised of PSMG1, PSMG2, PSMG3, and PSMG4) plays a critical role in proteasome biogenesis; however, its involvement in breast cancer remains poorly understood." (PMID 41869439, 2026). "Promising proteomic markers of breast cancer (SPG7, ADRB1, SMCO4, PHF1, and PSMG1) from NPCs identified in this study should be further verified in larger patient groups." (PMID 38138918, 2023). "Finally, we identified PSMG1, one of the genes co-expressed with NUP37, as having a highly positive relationship with NUP37 in The Cancer Genome Atlas- Breast Cancer (TCGA-BRCA) database using Xena." (PMID 34386417, 2021). "As this hypothesis is a novel finding in breast cancer, it is potentially expanding the cellular functions of NUP37 and PSMG1." (PMID 34386417, 2021).
inflammatory bowel disease (5 papers, 2020 to 2025). A spectrum of small and large bowel inflammatory diseases of unknown etiology. "We found several reports stating that PSMG1 increases susceptibility for inflammatory bowel diseases, which are linked to colon cancer." (PMID 32338277, 2020). "Recent studies indicate that PSMG1 heightens the risk of developing inflammatory bowel diseases." (PMID 40736072, 2025).
prostate carcinoma (4 papers, 2020 to 2025). A carcinoma that arises from epithelial cells of the prostate gland. "In addition, the targeting of PSMG1 caused by miR-484 inhibition resulted in decreased cell migration and invasion in prostate cancer." (PMID 38138918, 2023). "In addition, targeting PSMG1 caused by miR-484 inhibition led to reductions in cell migration and invasion in prostate cancer." (PMID 36619227, 2023). "Additional in vitro assays with cancer cell lines showed that PSMG1 knockdown rescued the reduction in mobility brought on by miR-484 inhibition, pointing toward the existence of a miR-484–PSMG1 axis in prostate cancer." (PMID 32338277, 2020). "Additionally, the researchers found PSMG1 plays an important role in cancer development and underscored the significance of the miR‐484–PSMG1 pathway in prostate cancer." (PMID 40736072, 2025). "In addition, elucidation of functions of PSMG1, other than proliferation and mobility, relevant to carcinogenesis would complement the current findings and establish the importance of miR-484–PSMG1 axis in prostate cancer." (PMID 32338277, 2020). "Thus, we postulate that miR-484 acts as an oncogene in prostate cancer by targeting PSMG1 and affecting cell mobility." (PMID 32338277, 2020). "While the present work shows that miR-484 is a candidate negative prognostic biomarker in prostate cancer likely by targeting PSMG1 and modulating cell mobility, its conclusions are based on analyses from patient samples and in vitro experiments using cancer cell lines, which have limitations." (PMID 32338277, 2020).
Alzheimer disease (2 papers, 2022 to 2025). A progressive, neurodegenerative disease characterized by loss of function and death of nerve cells in several areas of the brain leading to loss of cognitive function such as memory and language. "One locus overlapped with a known Alzheimer's disease GWAS locus (EED/PICALM) and 2 with GWAS loci for circulating ω-3 fatty acids (SRSF4 and PSMG1)." (PMID 40949174, 2025).
Down syndrome (2 papers, 2018 to 2024). "Notably, PSMG1, also known as Down Syndrome Critical Region Gene 2 (DSCR2), was implicated in Down Syndrome harboring trisomy 21, which was associated with an increased risk of developing AML." (PMID 39335660, 2024). "None of the enriched sets of pathways and functions associated with SCN1A was associated with the Down syndrome genes (DYRK1A, PSMG1, RCAN1, DSCR3, DSCR4) or with TSC2." (PMID 29518120, 2018).
ankylosing spondylitis (1 paper, 2025). An autoimmune chronic inflammatory disorder characterized by inflammation in the vertebral joints of the spine and sacroiliac joints. "We find for the first time that the rs4816648 SNP of the PSMG1 gene is associated with both susceptibility and severity of ankylosing spondylitis." (PMID 40736072, 2025). "Latest research on ankylosing spondylitis (AS) indicates a link between the B3GNT2, PSMG1 genes and susceptibility to AS among western populations." (PMID 40736072, 2025). "According to our studies, the rs4816648 SNP in the PSMG1 gene correlates with the vulnerability and intensity of ankylosing spondylitis." (PMID 40736072, 2025).
autism (1 paper, 2025). Persistent deficits in social interaction and communication and interaction as well as a markedly restricted repertoire of activity and interest as well as repetitive patterns of behavior. "While PSMG1 has not been directly linked to common NDDs, dysfunction of proteasome-associated genes such as PSMB1 and PSMC3 has been associated with autism, developmental delays, and microcephaly." (PMID 40869915, 2025).
lung carcinoma (1 paper, 2024). "High expression levels of PSMG4 were identified as a potential biomarker for adverse OS in lung cancer, while PSMG1 showed prognostic significance at the pan-cancer level." (PMID 39335660, 2024).
microcephaly (1 paper, 2025). A congenital or acquired developmental disorder in which the circumference of the head is smaller than normal for the person's age and sex. "Duplication involving PSMG1 and BRWD1 (Case 10) implicates disruptions in proteasome biogenesis and chromatin remodeling in patients with severe morphological anomalies and microcephaly." (PMID 40869915, 2025).
nephrolithiasis (1 paper, 2021). The presence of a calculus in the pelvis of the kidney; this is most often composed of mineral salts and proteins. "Several alleles associated with other traits of interest: rs2836882 near PSMG1 associated with ulcerative colitis, multiple SNPs including rs3923 near SLC17A1 associated with disorders in mineral metabolism, and rs17216707 near CYP24A1 associated with nephrolithiasis." (PMID 33547301, 2021).
vascular dementia (1 paper, 2025). A degenerative vascular disorder affecting the brain. "Loci CAMK2D and ATPase phospholipid transporting 8A2 (ATP8A2) were also replicated with these two exposures for vascular dementia, whereas loci iodothyronine deiodinase 2 (DIO2) and PSMG1 were replicated with oily fish intake and ω-3 concentrations." (PMID 40949174, 2025).
cancer (6 papers, 2020 to 2025). A tumor composed of atypical neoplastic, often pleomorphic cells that invade other tissues. "CONCLUSIONS: We hypothesize that miR-484 is an oncogene in the prostate that increases cancer cell mobility, with PSMG1 being a mir-484 target in this process." (PMID 32338277, 2020). "It was suggested that PSMG family member overexpression may promote tumor growth, and overexpression of PSMG1, PSMG3, and PSMG4 may further promote the development of cancer metastasis." (PMID 36619227, 2023).
tumor (3 papers, 2020 to 2023). "These evidence suggests that upregulation of PSMG1 may be able to promote tumor growth by activating 20S proteasome assembly and thereby degrading the tumor suppressors." (PMID 34386417, 2021). "The reduction would confirm the hypothesized tumor suppressive role of PSMG1 in reducing proliferation." (PMID 32338277, 2020).
PSMG1 also shares sentences with these, for which no sentence is quoted: colon cancer (2 papers); autoimmune disease (1); bladder cancer (1); Brain atrophy (1); cervical cancer (1); colorectal cancer (1); developmental delays (1); head and neck cancer (1); holoprosencephaly (1); infection (1); inflammatory liver disease (1); kidney renal cancer (1); liver cancer (1); lung adenocarcinoma (1); melanoma (1); ovarian carcinoma (1); pancreatic cancer (1); primary sclerosing cholangitis (1); ulcerative colitis (1).